PDK4 (pyruvate dehydrogenase kinase 4)
Diseases named in the same sentence as PDK4 in open-access papers (continued):
Sharing a sentence is not in itself a finding about the gene and the disease.
tumor (continued). "PDK4 was shown to facilitate the glycolysis of aerobic and cell proliferation of neoplasms." (PMID 34220962, 2021). "Nevertheless, considering the universal presence of PDK4 in both normal cells and tumor cells as well as the unsatisfactory pharmacokinetic features of DCA, new nanoformulation strategies are still urgently needed for enhancing the tumor‐targeted delivery of DCA." (PMID 34632727, 2021). "Interestingly, in vitro deletion of PDK4 protected cultured myotubes from tumor-conditioned medium-induced atrophy, suggesting PDK4 as a target to improve the mitochondrial homeostasis and the energetic status of cachectic mice." (PMID 34831373, 2021). "In summary, unlike the roles of PDK1-3, the roles of PDK4 in tumor progression and the underlying molecular mechanisms remain largely unclear." (PMID 32489458, 2020). "PDK4 expression is downregulated dramatically in most tumor types." (PMID 29921827, 2018). "Moreover, we performed data mining using the GEO database and found that PDK4 expression is significantly down-regulated in liver tumors compared to adjacent non-tumor liver tissues." (PMID 24376596, 2013). "Its deficiency has been shown to upregulate PDK4, which is located in the mitochondrial matrix, and the A isoform of LDH (LDHA), which is located in the cytoplasm, thereby leading to glycolysis upregulation, increased tumor cell migration, invasion and metastasis." (PMID 40801609, 2025). "Moreover, although our studies have affirmed that OA induced autophagy and inhibited glycolysis to attenuate OC progression by regulating the miR-122/PDK4 axis, it is still unclear whether OA also affects the immune cells in the tumor microenvironment of OC." (PMID 40969279, 2025). "Inhibiting glycolysis and limiting tumor metastasis in GC may be accomplished by suppressing PDK4." (PMID 38200513, 2024). "Thus, strategies combining a PDK4-targeting agent with classical chemotherapy hold the potential to enhance tumor responses without causing severe systemic cytotoxicity." (PMID 37903887, 2023). "Despite the correlation of higher PDK4 expression in tumor stroma with lower post-treatment survival, whether the metabolite lactate derived from stromal cells developing TIS is technically detectable and whether it can serve as a clinical marker, remains unclear." (PMID 37903887, 2023). "Our study established a PDK4 expression pattern upon cellular senescence, elucidated its role in diverging glucose metabolism toward glycolysis to produce lactate, and unraveled the correlation of PDK4 upregulation in tumor stroma and post-treatment patient survival." (PMID 37903887, 2023). "Thus, PDK4-targeted therapies may constitute a strategy to hinder cell survival in the tumor microenvironment and protect GC patients against tumor progression and metastasis." (PMID 35626257, 2022). "Furthermore, tumor purity may explain why PDK4 was upregulated in GC cells and downregulated in GC tissues." (PMID 35626257, 2022). "Therefore, whether PDKs such as PDK4 also play roles in the regulation of mitochondrial functions to regulate tumor metastasis remains to be investigated." (PMID 33446631, 2021). "Additionally, a recent study showed that HIF-1α can promote the expression of pyruvate dehydrogenase kinase 4(PDK4), further inducing macrophages polarize to M1 phenotype, which was described as a pro-inflammatory phenotype and tends to inhibit tumor progression." (PMID 32928258, 2020). "We did not observe any association between tumor stages and PDK4 expression levels." (PMID 25379179, 2014).
tumor (continued). "The overexpression of PDK4 and miR-122 effectively reversed the effects of OA and overexpressing PDK4 on the protein expression levels of Beclin-1, p62, GLUT1, and HK2 in the tumor tissue, respectively (P<0.05)." (PMID 40969279, 2025). "Initially, tumor tissues from DLBCL patients sensitive and resistant to rituximab chemotherapy were collected, and the expression and cellular localization of PDK4 in resistant tumor tissues were explored through immunohistochemistry." (PMID 39004737, 2024). "Compared to other groups, the aCD20@ExoCTX/siPDK4 group significantly reduced the green and yellow fluorescence intensities of PDK4 and p-HDAC8 in mouse tumor tissues, indicating that the expression of PDK4 and p-HDAC8 was inhibited in vivo." (PMID 39004737, 2024). "Currently understood activity of PDK4 on PDH, in addition to inhibitor studies, suggests that PDK4 should function as a positive regulator of tumor formation." (PMID 36980540, 2023). "A shift in energy metabolism towards glycolysis is also influenced by an increase in pyruvate dehydrogenase kinase 4 (PDK4), which in turn makes the tumor more aggressive, but reduces the efficiency of liver regeneration in a partial hepatectomy model." (PMID 39967915, 2023). "In vivo, SOGA1 and PDK4 knockdown both weakened overexpression of METTL116 elevated tumor growth, as reflected by tumor size, volume, and weight." (PMID 37340443, 2023). "Serving as a gatekeeper of the tricarboxylic acid (TCA) cycle by inactivating pyruvate dehydrogenase and pyruvate dehydrogenase kinase 4 (PDK4), LINC00243 has a significant role in tumor metabolism." (PMID 35757505, 2022). "METTL3 enhanced the stability of pyruvate dehydrogenase kinase 4 (PDK4) and HK2 mRNAs in a METTL3-m6A-YTHDF1-dependent manner, ultimately promoting tumor growth and chemoresistance." (PMID 33879256, 2021). "Tumor tissues with high c-Met expression level in TCGA have increased expression of H6PD, PDK2, PDK4, PDPR, PKLR, SLC2A2 genes whereas decreased expression of GYS1, HK1, HK2, SLC2A1, significantly." (PMID 34059694, 2021). "Mechanistically, β-asarone can reduce pyruvate dehydrogenase kinase (PDK) 1, phospho(p)-PDK1, PDK4, hypoxia-inducible factor 1-α (HIF1α), c-myc, STAT5, and p-STAT5 expression, which revealed how β-asarone affects tumor glycolysis." (PMID 32351601, 2020). "Taken together, in patients suffering advanced CRC, PDK4 expression was significantly more abundant in healthy liver and mucosa tissue than in corresponding CRLM- or primary tumour tissue." (PMID 30808993, 2019). "Additionally, the fluorescence intensity of PDK4 (green), p-HDAC8 (yellow), and CD20 (deep purple fluorescence) in the mouse tumor tissues was detected using immunofluorescence." (PMID 39004737, 2024). "Furthermore, G-Rh2 inhibited the tumor’s aerobic glycolytic capacity, including glucose uptake and lactate production, through the HIF1-α/PDK4 pathway." (PMID 38671369, 2024). "PDK4 level is regulated by E2F1 and influences tumor metabolism." (PMID 38371373, 2024). "PDK4 is a key enzyme regulating PDC activity, which is a crucial pyruvate oxidation and glucose maintenance homeostasis regulator in vivo, promoting the Warburg effect and tumor growth." (PMID 38554157, 2024). "However, the transcriptional profile changed in the tumor with a significant upregulation of ccRCC signature genes VEGFA, NDUFA4L2, and PDK4 both in the primary and the metastatic setting." (PMID 38281962, 2024). "For example, IGF1R, PDK4, and SOCS3 are involved in tumor proliferation, migration, and invasion." (PMID 39618816, 2024). "Although PDK4-IN administration did not provide noticeable benefits, MIT treatment caused notable tumor shrinkage (58.8% volume reduction), validating the efficacy of MIT as a cytotoxic agent." (PMID 37903887, 2023). "Future work will aim to understand how both canonical and non-canonical PDK4 activity reduces tumor growth and progression." (PMID 36980540, 2023).
tumor (continued). "Murine antibodies for PDK4 were not suitable for IHC, so instead, PDK4 was stained in a human tumor microarray." (PMID 36980540, 2023). "To assess why PDK4−/− tumors were larger, we initially hypothesized that PDK4−/− tumors may be resistant to apoptosis due to altered metabolism, leading to larger tumor size due to a reduction in cellular turnover." (PMID 36980540, 2023). "Histology indicated elevated SA-β-gal positivity in tumor tissues of mice that experienced MIT treatment, but exposure to PDK4-IN resulted in a lower SA-β-gal positivity, suggesting that PDK4 likely contributes to cellular senescence in animals undergoing chemotherapy." (PMID 37903887, 2023). "Also, the expression of PDK4 was detected in NSCLC tumor tissues, and the result presented that the expression of PDK4 at both mRNA and protein levels was abnormally higher in NSCLC tumor tissues (n = 45) relative to normal tissues (n = 45)." (PMID 34250255, 2021). "We here demonstrate for the first time that PCa patients with low PDK4 expression have a higher risk of earlier disease recurrence, independent of ISUP grading and tumor staging." (PMID 32323921, 2020). "PDK4 was identified as a tumor suppressor because its expression was markedly diminished in human HCC clinical specimens 17, 19, and the present study showed that PDK4 silencing by RNAi resulted in significantly enhanced proliferation, tumorigenicity, motility and invasion of HCC cells." (PMID 32489458, 2020). "Ascites-derived tumour cells exhibited enhanced CSC characteristics and PDK4 overexpression." (PMID 32390009, 2020). "The fact that basal-TNBC and CL-TNBC tumours had similar expression levels of MYC yet very different expression levels of CD36, LPL, PDK4 and FABP4 suggested that there are likely other factors, besides MYC, that direct activation of FAO and lipid metabolism in CL-TNBC." (PMID 31942031, 2020). "PDK4 transcript expression within healthy mucosa (surrounding primary tumours) did not affect patient survival (left)." (PMID 30808993, 2019). "Of note, Kaplan–Meier analysis of patients with PCa stratified according to PDK4 expression in the tumor stroma suggested a significant but negative correlation between PDK4 protein level and disease-free survival (DFS) in the treated cohort (P < 0.05, log-rank test)." (PMID 37903887, 2023). "One area that we did not fully explore mechanistically is the role of PDK4 in tumor inflammation." (PMID 36980540, 2023). "The dependency/capacity of each tumor on de novo fatty synthesis may be a predictor of whether or not PDK4 acts as a tumor suppressor, although additional studies are needed in this area across a broader range of tumors." (PMID 36980540, 2023). "While the urothelium in normal tissue stained positive for PDK4, it was largely absent in the majority of tumor specimens Scoring tumors via H index demonstrated a statistically significant reduction in PDK4 expression in the epithelium compared to WT controls." (PMID 36980540, 2023). "The advent of numerous PDK4 client substrates offers the possibility that a significant biological activity remains under investigation and may be highly relevant to future studies, particularly in regard to the ability of PDK4 to suppress tumor formation rather than enhance it." (PMID 36980540, 2023). "In addition, xenografts with EV showed significant tumor shrinkage after treatment with rituximab in terms of tumor weight (P = .029) and tumor volume (P = .0019), whereas those with PDK4 OE did not have significantly reduced tumor weight (P = .158) or tumor volume (P = .083)." (PMID 34252986, 2021). "Thus, targeting PDK4 alone affects neither tumor growth nor animal survival, whereas MIT/PDK4-IN co-treatment has the competence to significantly improve both parameters." (PMID 37903887, 2023).
metabolic disease (19 papers, 2014 to 2025). A congenital disorder (due to inherited enzyme abnormality) or acquired (due to failure of a metabolically important organ) disorder resulting from an abnormal metabolic process. "This concept involves the metabolic disorders–cytokine cycle, which is interconnected with metabolite-mediated signaling pathways and transcription factors, such as PPARs, and PDK4, and in turn is closely linked to the influenza virus–cytokine–trypsin cycle for viral proliferation through cytokines." (PMID 24865588, 2014). "Since the incapacity of insulin to downregulate PDK4 has been demonstrated in obese and diabetic subjects, the consequent increase in the PDK4 levels associated with an inappropriate suppression of the PDHC activity may promote the development of metabolic diseases." (PMID 29535681, 2018). "They reported that PDK4 is almost invariably upregulated in mitochondrial dysfunction-related metabolic diseases." (PMID 35372351, 2022). "A novel methylation marker, cg17075888 (PDK4) also seemed intriguing, since this gene was extensively researched for potential therapeutic targets; a PDK4 inhibitor has been reported as a potential drug target for metabolic diseases, such as T2D." (PMID 32709145, 2020). "Another enzyme being specifically correlated to metabolic disease and gluconeogenic gene expression, the mitochondrial protein pyruvate dehydrogenase kinase 4 (Pdk4), was strongly inhibited in livers of mice treated with HDAC4/5/7 siRNAs." (PMID 32982982, 2020). "Notably, PDK4 is upregulated in metabolic diseases related to mitochondrial dysfunction, particularly in pathologic muscle conditions associated with defective myogenesis." (PMID 40410591, 2025). "As an increase in the PDHC activity by a PDK4 inhibitor promotes glucose oxidation and lowers the blood glucose concentration, small molecule inhibitors for PDKs are promising therapeutic agents for patients with metabolic diseases." (PMID 29535681, 2018). "Moreover, miR-33 and miR-122, which are commonly altered in metabolic disorders, have been demonstrated to directly target PDK4 in the macrophages to promote cholesterol efflux and reduce atherosclerosis and in the CD133 (+) hepatocellular cancer stem cells, respectively." (PMID 29535681, 2018). "The FoxO1/PDK4 pathway inhibits glucose utilization in skeletal muscle by regulating PDHC activity, which eventually results in metabolic diseases." (PMID 36986243, 2023). "Our results identify FXR as a nuclear transcription factor that regulates glucose and lipid metabolism balance through PDK4, providing further insights into the mechanism of FXR agonists in the treatment of metabolic diseases." (PMID 35251469, 2022). "As an extension to our previous studies, we added in the present study a new evidence for the marked up-regulation of PDK4 in IAV infection with suppression of PDH activity and ATP levels in the mitochondria, in addition to metabolic disorders and MOF in mice." (PMID 24865588, 2014). "DADA selectively and effectively inhibited PDK4, resulting in significant restoration of PDH activity as well as various metabolic disorders, such as ATP levels in various organs, and improved glucose, lactate and β-hydroxybutyric acid levels in the blood." (PMID 24865588, 2014). "The role of PDK4 in muscle tissues of well-fed animals without metabolic disorders is secondary, and the major isozyme in these tissues is PDK2." (PMID 40943218, 2025). "Due to the lack of commercially available PDK4 selective inhibitors, pharmacological pan-PDK inhibitors, such as dichloroacetate (DCA), which target the ATP-binding pockets of all PDK isozymes, have been used to investigate metabolic diseases associated with mitochondrial dysfunction." (PMID 39122684, 2024).
metabolic disease (continued). "Pyrosequencing analyses were performed for the candidate genes KCNJ11, PPARγ, PDK4, KCNQ1, SCD1, PDX1, FTO and PEG3 in peripheral blood leukocytes (PBLs) from 25 patients diagnosed with only T2D, 9 patients diagnosed with T2D and MetS and 11 control subjects without any metabolic disorders." (PMID 28727822, 2017).
infection (7 papers, 2014 to 2025). The state of being infected such as from the introduction of a foreign agent such as serum, vaccine, antigenic substance or organism. "We then used the PDK4 inhibitor sodium dichloroacetate (DCA) to pretreat the cells with ΔCcpA S. aureus for 12 h before infection." (PMID 38003764, 2023). "Administration of diisopropylamine dichloroacetate (DADA), an inhibitor of PDK4, significantly delayed mortality from the infection." (PMID 33014275, 2020). "Both Akt1 and Akt2 were demonstrated to phosphorylate PDK1, and PDK4 expression was markedly inhibited by infection with shRNA directed against Akt1." (PMID 31398213, 2019). "Consistent with this, Pdk4, the major kinase responsible for cardiac PDH phosphorylation, was elevated in vehicle-pretreated mice during infection compared to fluoxetine-pretreated mice." (PMID 39951524, 2025). "It is well known that PDK4 is up-regulated by low food intake and the pathological findings induced by IAV infection may be the complex outcome of viral proliferation, cytokine storm and PDK4 up-regulation associated with the lack of food intake after infection." (PMID 24865588, 2014). "Upon verification in the animal model, we found that infection with the XN108 ΔCcpA strain increased the transcription and translation of PDK4 in the liver of type 1 diabetic mice, increased p-PDH expression, and significantly increased the pyruvate level in the tissues." (PMID 38003764, 2023).
cardiovascular disease (6 papers, 2015 to 2025). "These associations demonstrate that Pdk4 plays a crucial role in improving mitochondrial function and cardiovascular disease through mediating oxidation metabolism, autophagy, oxidative stress, and mitochondrial dynamics." (PMID 38547044, 2024).
heart disease (4 papers, 2020 to 2021). "The pharmacological effects of adropin on energy metabolism and PDK4 in the heart and cardiomyocytes, indicating that adropin may be a putative candidate for the treatment of cardiac disease associated with impaired insulin sensitivity." (PMID 33739396, 2021). "Elevated levels of PDK4 and thioredoxin interacting protein (TXNIP), and decreased expression of the array of genes associated with both heart diseases and compromised glucose metabolism were observed." (PMID 32804947, 2020). "Our study demonstrated that PDK4 could be used as a potential target for clinical diagnosis and treatment of pediatric heart disease." (PMID 34517782, 2021).
immune disorders (3 papers, 2021 to 2024). "It was obvious that the up-regulation of PDK4 aggravated cardiac dysfunction, immune dysfunction and cardiomyocyte apoptosis in immature rats with MI/R injury." (PMID 34517782, 2021). "Accordingly, silenced PDK4 attenuated cardiac dysfunction, immune disorder and myocardial apoptosis in immature rats and enhanced the ability of antioxidant enzymes." (PMID 34517782, 2021). "Taken together, the results of this study suggest that overexpressed miR-148 can reduce cardiac dysfunction, immune disorder and cardiomyocyte apoptosis in immature MI/R rats by targeting PDK4 and inhibiting its expression." (PMID 34517782, 2021). "Taken together, our study demonstrated that overexpressed miR-148 relieved cardiac dysfunction, immune disorder and cardiomyocyte apoptosis in immature MI/R rats by PDK4 inhibition, which provided novel targets for MI/R injury treatment." (PMID 34517782, 2021). "The miR-148/PDK4/SMAD pathway relieved the MI/R injury through regulating the cardiac dysfunction, immune disorders and myocardial apoptosis." (PMID 34517782, 2021).
neurodegenerative disease (2 papers, 2021 to 2025). A disorder of the central nervous system characterized by gradual and progressive loss of neural tissue and neurologic function. "The antagonistic effect of increased PDK4 on mitochondrial ATP production and functionality suggests that this could be one of the contributing factors in this neurodegenerative disease." (PMID 40730554, 2025).